CYP2G1P (cytochrome P450 family 2 subfamily G member 1, pseudogene )
Synonyms: CYP2G1; CYP2GP1
Gene: Long non-coding RNA gene on chromosome 19 (40,890,826 to 40,912,357, forward strand). Ensembl gene ENSG00000290611.
Diseases named in the same sentence as CYP2G1P in open-access papers:
CYP2G1P is named in the same sentence as 1 disease in open-access papers, as found by Europe PMC text mining. Sharing a sentence is not in itself a finding about the gene and the disease.
CYP2G1P shares sentences with these, for which no sentence is quoted: depression (1 paper).